C8A (complement C8 alpha chain)
Description:
Component of the membrane attack complex (MAC), a multiprotein complex activated by the complement cascade, which inserts into a target cell membrane and forms a pore, leading to target cell membrane rupture and cell lysis. The MAC is initiated by proteolytic cleavage of C5 into complement C5b in response to the classical, alternative, lectin and GZMK complement pathways. The complement pathways consist in a cascade of proteins that leads to phagocytosis and breakdown of pathogens and signaling that strengthens the adaptive immune system. C8A, together with C8B and C8G, inserts into the target membrane, but does not form pores by itself. During MAC assembly, associates with C5b, C6 and C7 to form the C5b8 intermediate complex that inserts into the target membrane and traverses the bilayer increasing membrane rigidity.
Tractability: Antibody: UniProt places it where antibodies can reach, with high confidence; its Gene Ontology location is reachable by antibodies, with high confidence; UniProt predicts a signal peptide or a membrane-spanning region; the Human Protein Atlas places it where antibodies can reach. PROTAC: its protein half-life has been measured.
Gene: Protein-coding gene on chromosome 1 (56,854,768 to 56,918,223, forward strand). Ensembl gene ENSG00000157131.
Subcellular location: Secreted; Target cell membrane
Subcellular location (Human Protein Atlas): Plasma membrane; Predicted to be secreted
Pathways (Reactome):
Immune System: Regulation of Complement cascade; Terminal pathway of complement
Gene Ontology:
Molecular function: protein binding; wide pore channel activity; complement binding; protein-containing complex binding
Biological process: complement activation; complement activation, GZMK pathway; killing of cells of another organism; immune response; positive regulation of immune response; transmembrane transport
Cellular component: blood microparticle; extracellular exosome; extracellular region; membrane attack complex; other organism cell membrane; plasma membrane; membrane
Genetic constraint (gnomAD): Loss-of-function variants: 71 observed, 74.09 expected, observed/expected ratio (o/e) 0.96, 90% interval 0.79 to 1.17. The upper end of that interval is the gene's LOEUF score, 1.17, which puts it in group 5 of 6, group 1 being the genes least tolerant of losing a copy. Missense variants: 781 observed, 763.03 expected, observed/expected ratio (o/e) 1.02, 90% interval 0.96 to 1.09. Synonymous variants: 290 observed, 274.52 expected, observed/expected ratio (o/e) 1.06, 90% interval 0.96 to 1.16.
Homologues: Orthologues: macaque C8A (95% identical), chimpanzee C8A (83% identical), pig C8A (79% identical), dog C8A (78% identical), rabbit C8A (78% identical), guinea pig C8A (77% identical), rat C8a (74% identical), mouse C8a (73% identical), tropical clawed frog c8a (50% identical). Paralogues in human: C8B (32% identical), C6 (30% identical), C7 (28% identical), C9 (26% identical), PAPPA2 (17% identical), CSMD3 (16% identical), CSMD2 (16% identical), CSMD1 (16% identical), PRF1 (15% identical), PAPPA (15% identical), CFH (14% identical), SVEP1 (14% identical), and 27 more.
Diseases named in the same sentence as C8A in open-access papers:
C8A is named in the same sentence as 17 diseases in open-access papers, as found by Europe PMC text mining. Sharing a sentence is not in itself a finding about the gene and the disease. The quoted sentences say what the papers report.
glaucoma (2 papers, 2017 to 2024). Increased pressure in the eyeball due to obstruction of the outflow of aqueous humor. "We quantified the majority of key proteins associated with classical complement pathway, such as C1q, C1s, C1r, C4a, C4b, C3, C5, C6, C7, C8a, C8b, C8g and C9, as up-regulated in glaucoma condition for both vitreous and retinal tissues when compared to the controls." (PMID 28978942, 2017).
autism (1 paper, 2024). Persistent deficits in social interaction and communication and interaction as well as a markedly restricted repertoire of activity and interest as well as repetitive patterns of behavior. "Six genes were significantly differentially expressed between autism likelihood (social communication) groups: CYSLTR2, NOX1, C1QA, CXCL10, C8A, IL23R (all up-regulated, p < 0.05)." (PMID 39247132, 2024).
Listeria infection (1 paper, 2021). "Eight of these genes were similarly inhibited by Listeria infection in PMH: they encode (i) the activating enzyme C1S of the C1 complex, (ii) the central component C3, (iii) the membrane-attack proteins C6 and C8A, and (iv) four complement regulators (C1QTNF6, CFH, CFHR2, VTN)." (PMID 34858876, 2021).
schizophrenia (1 paper, 2022). A major psychotic disorder characterized by abnormalities in the perception or expression of reality. "Accompanying the metabolic disruption identified in patients with schizophrenia was an increase in several complement effector proteins, including C4a/b, C5, C6, C8a, and C9." (PMID 34741130, 2022).
Stroke (1 paper, 2020). Sudden impairment of blood flow to a part of the brain due to occlusion or rupture of an artery to the brain. "Specifically, elements of the alternative pathway of complement system and MAC proteins, i.e., CFI, C6, C8A, C8G, C9 were found to be activated but also undergoing regulation at 3 months post-stroke." (PMID 32849183, 2020).
cancer (4 papers, 2018 to 2024). A tumor composed of atypical neoplastic, often pleomorphic cells that invade other tissues. "Plasma protein levels of 11 proteins, including complement C8A and serpin family A member 4 (SERPINA4) were linked to cancer-associated inflammation, while 4 proteins, including C8A and C4B, distinguished early from advanced CRC stages." (PMID 38911905, 2024). "A third protein-protein interaction network in the blood cancer patient group includes genes associated with the complement system such as C1S, C3 and C8A, activation of which is mainly associated with pro-tumour effects." (PMID 36649303, 2023). "First, correlation analysis determined significant correlation of 18 proteins with cancer-associated inflammation, including 9 proteins correlated positively such as C8A, A2GL, and ceruloplasmin (CERU), while another 9 proteins including retinol-binding protein 4 (RET4) were correlated negatively." (PMID 38911905, 2024). "From the GeneAtlas, C8A mRNA is highly expressed only in liver tissue, and the Cancer Cell Line Encyclopedia indicates a wide range of C8A mRNA expression in cancer cell lines." (PMID 32913993, 2018). "We also characterized C8A protein expression in stable cancer cell lines." (PMID 32913993, 2018).
infection (3 papers, 2015 to 2025). The state of being infected such as from the introduction of a foreign agent such as serum, vaccine, antigenic substance or organism. "Furthermore, a broad activation pattern of the complement system—encompassing both effector components (e.g., C2, C3, C8A, C9) and regulatory proteins (e.g., CFH, CFI, C1QB)—is consistent with prolonged innate immune stimulation in the absence of active infection." (PMID 40869330, 2025).
tumor (2 papers, 2015 to 2023). "We next randomly selected 8 genes aberrantly expressed in HCCs that had aberrant DNA methylation (CR1, ESR1, PTPN13, and SOCS2) or SCNA (C8A, CXCL14, ITGA6 and MARCO) to validate the array-based results in an independent sample set consisting 47 HCCs and paired non-tumor specimens." (PMID 25965583, 2015).
C8A also shares sentences with these, for which no sentence is quoted: adenoma (1 paper); COVID-19 (1); lung adenocarcinoma (1); lymphoma (1); malaria (1); periodontitis (1); Sepsis (1); staphylococcus aureus infection (1); thyrotoxicosis (1).